EPO (erythropoietin)
Diseases named in the same sentence as EPO in open-access papers (continued):
Sharing a sentence is not in itself a finding about the gene and the disease.
tumor (continued). "Moreover, the downstream products of the HIF-1α signaling cascade include vascular endothelial growth factor (VEGF), erythropoietin (EPO), and insulin-like growth factor 2 (IGF2), involved in tumor-induced angiogenesis." (PMID 38791432, 2024). "The significance of VEGF, EPO, and angiopoietin-2 in tumor nutrition and metastasis is well documented, suggesting that ALA may exert a limiting effect on tumor growth and metastasis." (PMID 39199143, 2024). "Additionally, the mesenchymal characteristics of GBM are mediated by the EPO secreted by GBM, which can act on the EPOR of microglia and oligodendrocytes in the microenvironment, promote tumor survival, proliferation, and angiogenesis." (PMID 37692522, 2024). "In the context of GBM, HIF-1a plays a role in regulating tumor metabolism and increases GBM aggressiveness by promoting angiogenesis via upregulation of vascular endothelial growth factor (VEGF), erythropoietin (EPO), and platelet-derived growth factor (PDGF) family proteins." (PMID 38727262, 2024). "Erythropoietin accumulation was not due to erythropoietin secretion by a tumor as no obvious lesions were detected on contrast-enhanced computed tomography." (PMID 36890599, 2023). "EPO-dependent cells that do not give rise to subcutaneous tumours, with no autonomous proliferation, are considered as preleukaemic cells." (PMID 37573408, 2023). "It was previously shown that cells isolated from the bone marrow and spleen of sick TgSpi1 mice required the erythroid growth factor erythropoietin (EPO) to be maintained in culture and did not give rise to tumour after subcutaneous engraftment." (PMID 37573408, 2023). "Although EPO treatment of wild-type A549 tumor-bearing mice did not alter tumor growth or respiratory control, the loss of EPOR per se reduced tumor growth and mitochondrial density with an unabated respiratory potential." (PMID 36052260, 2022). "EPO treatment increased erythropoiesis in all mice but did not increase tumor progression, weight, or volume." (PMID 36052260, 2022). "Similar to tumor growth, EPO treatment did not alter cellular respiration but the loss of EPOR reduced cellular respiration in A549 tumors." (PMID 36052260, 2022). "On the other hand, there are also studies showing that EPO has no direct stimulatory effect on tumor cell growth." (PMID 36567722, 2022). "Importantly, J-CDs were compared with EPO in several cancer cell lines and a NOD/SCID xenograft tumor model." (PMID 36518596, 2022). "Moreover, genes which regulate cell death or anaerobic glycolysis appear to be predominantly controlled by HIF-1α, but genes which regulate erythropoietin synthesis (EPO) and tumor stemness or pluripotency are primarily regulated by HIF-2α." (PMID 36003773, 2022). "Since S100A2 plays a role in regulating tumor development in almost all tumors, the interaction of S100A2 with erythropoietin might be important in certain conditions, such as erythropoietin-dominant tumor development." (PMID 35885660, 2022). "The recombinant human erythropoietin competes with ephrin-B2 for binding to EPHB4, and therefore, the tumor progression might be mediated via EPO-induced phosphorylation of EPHB4 and subsequent activation of downstream signaling, independent of the EPOR." (PMID 35694408, 2022). "The first is to increase tumor oxygen levels, which can be achieved by inducing angiogenesis and erythropoiesis through the transcription of proangiogenic genes, such as vascular endothelial growth factor (VEGF) and erythropoietin (EPO)." (PMID 34885069, 2021). "Our findings suggest that EPO may contribute to relapses and overall NB progression, and HGF and NGF might contribute to metastases’ formation and tumor cell survival during therapy." (PMID 34556815, 2021).
tumor (continued). "The suppressive effects of 2 and 7 on HIF‐1α‐mediated gene transcription were investigated based on changes in the mRNA levels of the HIF‐1α downstream targets VEGF, glucose transporter‐1 (Glut1), and erythropoietin (EPO), which are crucial for tumor progression and angiogenesis." (PMID 33955074, 2021). "In particular, hypoxic conditions are known to control the expression of target genes such as VEGF, TGF-β2, MMP-1,2, and 9, human plasminogen activator inhibitor type 1, endothelin-1, and erythropoietin (EPO), influencing angiogenesis, tumor growth, and GBM invasiveness." (PMID 33020459, 2020). "Tumor cells promote angiogenic activity through increases in hypoxia-inducible factor 1α (HIF-1α), vascular endothelial growth factor (VEGF), erythropoietin (EPO), cyclin D1 protein expression, which are essential for tumor growth." (PMID 30678221, 2019). "Tumor cells produce hypoxia-inducible factor (HIF) as an important mediator of tumor metabolism, which regulates the expression of target genes, such as erythropoietin, iron metabolism-related genes, VEGF, GLUT1, glycolytic enzymes, heme oxygenase HO2-1, and inducible nitric oxide synthase." (PMID 31142326, 2019). "Several studies identified pro-stimulating EPO/EPOR effects in tumor cells; however, numerous studies opposed this fact due to the usage of unspecific EPOR antibodies and thus potential absence or very low levels of EPOR in tumor cells." (PMID 30606107, 2019). "There are many studies demonstrating that EPO/EPOR signalization in cancer cells can: induce cell proliferation, change the sensitivity to chemotherapeutics, induce angiogenesis and/or tumor neovascularization." (PMID 30606107, 2019). "On the contrary, preoperative administration of EPO stimulated tumor recurrence in an animal model of colon cancer without evidence of increased angiogenesis or enhanced cell proliferation." (PMID 28703764, 2017). "In this regard, EPO induces angiogenesis in chemically induced murine hepatic tumors and accelerates the growth of EPOR-negative Lewis lung carcinoma cells by promoting tumor angiogenesis in vivo." (PMID 28703764, 2017). "In this study, we did not observe changes in tumor capillary densities after local EPO blockage or EPOR knockdown (data not shown)." (PMID 29137269, 2017). "EPO activates the expression of PI3K/AKT and MAPK pathways in tumor cells." (PMID 28418910, 2017). "Although some studies have not confirmed a direct stimulatory effect of EPO on tumor cells, there is ample evidence of this effect on the proliferation of ECs and/or angiogenesis of tumors." (PMID 28703764, 2017). "In a separate study however, EPO does not affect breast tumor cells but promote self-renewal of tumor-initiating cell." (PMID 29137269, 2017). "Local blockage of EPO signaling could suppress the growth of dual EPO and EPOR-positive NSCLC tumor and prolong survivals of xenograft mice." (PMID 29137269, 2017). "This indicates that EPO might not only have an effect on erythroid progenitor cells, but also could induce EPO-mediated survival signaling in other cells expressing the EPOR, including tumor cells." (PMID 27494133, 2016). "The mean (SD) CD31- microvessel density (MVD) in the tumor specimens was 22.3 (13.02) in control DLD-1 xenografts, 40.0 (16.9) in erythropoietin treatment DLD-1 xenografts, 2.0 (3.5) in control Ht-29 xenografts and 2.3 (6.3) in Ht-29 xenografts receiving erythropoietin." (PMID 27543111, 2016). "The lack of increased serum EPO from S-HBs suggests localized EPO signaling (autocrine/paracrine) driving focal areas of tumor proliferation through induced HIF-2α." (PMID 27748427, 2016). "Thus the increased EPO-R signaling with STAT-5 induced HIF-2α and resultant EPO upregulation and activation seen in focal stromal cells suggests an EPO-HIF-2α signaling loop driving local tumor evolution." (PMID 27748427, 2016).
tumor (continued). "As for muscle function, the reduced muscle strength found in tumor-bearing animals is not modified by the two week exercise protocol, independently of EPO treatment." (PMID 26636649, 2015). "Of interest, exercise, associated or not with EPO, increases SDH activity also in comparison with control mice, suggesting that the tumor-bearing condition is permissive for muscle mitochondrial biogenesis." (PMID 26636649, 2015). "Recently, EPO has been not validated for post-radiation therapy because previous clinical trials revealed potential adverse effect of EPO on tumor control." (PMID 26610477, 2015). "In contrast, no activation by human recombinant erythropoietin was observed in isolated tumor cells." (PMID 25807104, 2015). "Although some studies have not confirmed a direct stimulatory effect of EPO on tumor cells, there is ample evidence of this effect on endothelial cell proliferation and/or angiogenesis of tumors." (PMID 25426117, 2014). "As suggested in other recent studies, however, the overall direct effect of EPO/EPOR signaling on tumor progression and therapy is not straightforward." (PMID 24155958, 2013). "Primary tumour site, liver and peritoneal metastases, age and gender did not correlate with Hb response to EPO." (PMID 22950685, 2012). "Primary tumour site, liver metastases, peritoneal metastases, age, gender did not correlate with HB response to EPO." (PMID 22950685, 2012). "This is not surprising because preclinical data suggest that EPO is a very powerful promoter of tumor cell growth and is able to promote neovascularization to the site of the tumor, which can potentially increase metastasis." (PMID 21943500, 2011). "G-CSF and EPO are never used clinically before a primary therapy because of their ability to promote tumor growth [personal communication from D. Douer], and TPO and SCF, which are no longer being pursued clinically, also proliferate tumor cells." (PMID 18489769, 2008). "Quantification of tumor neovascularization revealed significant stimulation of angiogenesis in erythropoietin-treated window chambers compared to buffer-treated negative controls." (PMID 17579721, 2007). "In previous studies, systemically administered rEPO over a 3 to 4 week period did not enhance the growth of various types of tumor xenografts, including R3230 tumors, despite the ability of erythropoietin to activate intracellular signaling in the cells." (PMID 17579721, 2007). "Since several tumour cell lines express an EPO receptor, it has been discussed that erythropoietin may promote tumour growth." (PMID 15305198, 2004). "The baseline erythropoietin O/P ratio was only predictive of response for patients with nonsolid tumours." (PMID 12671693, 2003). "These cases highlight that serum EPO levels do not necessarily correlate with tumor size." (PMID 41487860, 2025). "This discrepancy suggests that tumor weight does not directly predict serum EPO levels." (PMID 41487860, 2025). "This could be explained by the negative feedback mechanism of the abnormally secreted EPO from the tumor cells." (PMID 38534956, 2024). "A notable limitation of the EPO-GEMM approach is that it does not provide precise control over the cell of origin for tumor development and could induce somatic alterations in stromal cells." (PMID 38177458, 2024). "On the other hand, in OSCC, tumor progression and metastasis are also sustained by the presence of hypoxia-inducible factor (HIF) and related genes induced by hypoxia, such as VEGF, interleukin 1A (IL-1A), endothelin 1, platelet-derived growth factor B (PDGFB) and erythropoietin (EPO)." (PMID 35890188, 2022). "EPO has no immediate stimulatory effect on tumor cell growth." (PMID 36567722, 2022).
tumor (continued). "However, clinical trials have demonstrated worse tumor control in HNSCC patients treated with EPO and found that EPO can promote lymphatic tract metastasis in HNSCC through mediated activation of JAK-STAT signaling, thereby enhancing tumor aggressiveness, which is detrimental to patient prognosis." (PMID 36406133, 2022). "By contrast, the EPO-GEMM approach enables the production of autochthonous tumors in immunocompetent mice that naturally disseminate, enabling the relatively synchronous production of cohorts of tumor-bearing mice simply from a set of plasmids and commercially available immunocompetent WT mice." (PMID 35082152, 2022). "New EPO/EPOR target genes in cancer cells could serve as markers for various means of monitoring both disease activity and cell responses to various therapies, including the administration of rHuEPO to tumor patients." (PMID 34281163, 2021). "Additionally, the HIF2α transcriptional targets EDN1, EPO, GNA14, and VEGFA were significantly upregulated in the tumor and might also promote tumor progression." (PMID 32235007, 2020). "Both patients were found to be negative for mutations in erythropoietin, erythropoietin receptor, HIF-1α, janus kinase 2, prolyl hydroxylase, succinate dehydrogenase B/C/D, and von Hippel-Lindau genes in circulating leukocytes and resected tumor tissues." (PMID 31185588, 2019). "Based on the current literature, the influence of EPO/EPOR on different cancer types appears to be variable and remains incompletely understood and more functional studies are needed to determine whether EPOR activation modifies tumor cell growth." (PMID 28415825, 2017). "However, existence and relevance of these regulatory phosphorylation events in EPO-mediated signaling pathways leading to tumor progression has not been explored." (PMID 28415825, 2017). "However, contrary to observations in other tumor cells, Stat3 and Stat5 were not involved in EPO-signaling in B16 cells." (PMID 28415825, 2017). "For HCC15, EPO-NA treatment neither inhibited tumor growth nor reduced Ki67 labeling." (PMID 29137269, 2017). "One can cite quercitin, berberin derivatives (EPO Patent 0813872-A1), paclitaxel, KNK437 and interferon-γ which suppresses HspB1 basal transcription and promoter activity thus enhancing hyperthermia-induced tumor cell death in vitro and tumor suppression in vivo." (PMID 24514166, 2014). "However, administration of EPO in Caki-1 xenografts did not result in a tumor growth advantage compared to controls (p = 0.20)." (PMID 24004818, 2013). "EPOR rather than EPO may be upregulated by hypoxia in the tumor bed, and the high expression of EPOR in the tumor tissue may promote neck lymph node metastasis." (PMID 22639817, 2012). "However, only patients in whom imatinib induces tumor control were found to respond to EPO, and none of the patients progressing under imatinib achieved Hb response to EPO." (PMID 22950685, 2012). "Similarly, another meta-analysis indicated that when used within current European Organisation for Research and Treatment of Cancer (EORTC) treatment guidelines, the ESA epoetin-β (EPO) had no negative impact on survival and tumour progression." (PMID 21959870, 2011). "Among these biomolecules, vascular endothelial growth factor and erythropoietin are maturation factors for tumor angiogenesis, and these HIF-1 α-induced factors create a pro-angiogenic microenvironment in SCC, which may promote angiogenesis, tumor growth, and possibly metastatic affinity." (PMID 39421442, 2024). "All this evidence suggests that EPOR, like EPO, may play a non-negligible role in tumor immunity." (PMID 35359375, 2022). "Neither presence of RCC, EPO-level, associated tumor cysts nor VHL-mutation (truncating versus non-truncating) had any significant impact in predicting polyglobulia By performing multivariate binary regression again only tumor volume was a robust independent predictor for polyglobulia." (PMID 30214643, 2018).
tumor (continued). "Importantly, these studies could not address erythropoietin-dependent EpoR function in tumor tissue." (PMID 25807104, 2015). "Based on these molecular observations and the present case report, we hypothesized that EPO produced by RCC cells raises the levels of circulating HSCs and the vascular endothelium-rich RCC acts as a niche that allows circulating HSCs to colonize within the tumor and initiate BM formation." (PMID 24520308, 2014). "Unlike hematopoietic cells, where EPO-EPOR signaling is associated with increased cell proliferation and/or survival, in tumor cells, the EPO-EPOR axis does not always lead to increased proliferation but might increase the resistance of cancer cells to different therapies." (PMID 25426117, 2014). "Abdominal ultrasound may be helpful to rule out an EPO-producing tumour." (PMID 24312736, 2013). "HIF-2α transcriptional targets EDN1, EPO, GNA14, and VEGFA were significantly upregulated in the tumor bed but not the surrounding liver tissue, indicating hyperactivation of the hypoxia signaling pathway within the tumor." (PMID 32235007, 2020). "HIF-2α target genes EDN1, EPO, GNA14, and VEGF were significantly upregulated in the tumor bed but not in the surrounding liver tissue." (PMID 32235007, 2020). "In this regard, EPO xinduced angiogenesis in chemically induced murine hepatic tumors and accelerated the growth of EPOR negative Lewis lung carcinoma cells by promoting tumor angiogenesis in vivo." (PMID 25426117, 2014). "Importantly, EPO stimulation increased BCSC survival and resistance to chemotherapeutic agents, probably by EPO-activated AKT and ERK pathways and promoted metastatic progression of tumor xenografts in the presence and in the absence of chemotherapy treatment." (PMID 25426117, 2014). "Co-expression of erythropoietin (Epo) and erythropoietin receptor (EpoR) has been found in various non-hematopoietic cancers including hereditary and sporadic renal cell carcinomas (RCC), but the Epo/EpoR autocrine and paracrine mechanisms in tumor progression have not yet been identified." (PMID 23028796, 2012).